DENND6A-DT (DENND6A divergent transcript)
Gene: Long non-coding RNA gene on chromosome 3 (57,693,179 to 57,696,596, forward strand). Ensembl gene ENSG00000241933.
Gene Ontology:
Biological process: SRP-dependent cotranslational protein targeting to membrane, signal sequence recognition
Cellular component: signal recognition particle, endoplasmic reticulum targeting